GATA4 (GATA binding protein 4)
Diseases named in the same sentence as GATA4 in open-access papers (continued):
Sharing a sentence is not in itself a finding about the gene and the disease.
heart failure (continued). "Cardiac specific knockout of GATA4 in adult mouse renders the heart less able to hypertrophy with agonist or pressure overload stimulation, as well as more likely to succumb to heart failure." (PMID 25093027, 2014). "Inhibition of GATA4 – a cardiomyocyte survival factor – by caspase-1 is consistent with the reported involvement of caspase-1 in myocyte cell death and heart failure." (PMID 25501827, 2014). "We have shown previously that heart-specific deletion of Gata4 in the adult mouse renders the heart less able to hypertrophy with agonist or pressure overload stimulation, as well as more likely to succumb to heart failure, even with aging." (PMID 24391969, 2013). "Therefore, the inhibition of GATA4 homomultimerization can serve as a potential therapeutic strategy for heart failure, as can the inhibition of GATA4 acetylation and phosphorylation." (PMID 35173540, 2022). "In addition, alterations in the GATA4 signaling pathway have been frequently observed in various age-related diseases, including atherosclerosis (AS) and heart failure (HF)." (PMID 36177479, 2022). "Furthermore, overexpressed wildtype acetyltransferase p300 in myocardial infarcted hearts increases GATA4 acetylation that contributes to worst cardiac pathologies in this murine model of heart failure." (PMID 34831061, 2021). "We previously found both that curcumin suppresses cardiomyocyte hypertrophy by inhibiting the acetylation of GATA4 and histones, and that the oral administration of curcumin at a dose of 50 mg/kg prevents the development of heart failure in rat models of hypertension and myocardial infarction." (PMID 32346115, 2020). "Curcumin treatment impedes the acetylation of GATA4 by p300 to hinder their interaction and disrupts the downstream fetal gene program in adult murine cardiac tissue subjected to hypertensive and hypoxic injury to significantly improve heart failure outcomes." (PMID 24790981, 2014). "Therefore, GATA4 multimerization may be increased in the hearts of human heart failure patients, together with increased GATA4 acetylation." (PMID 35173540, 2022). "A disease-causing GATA4 mutation is shown to diminish PGC-1α/ERR/GATA4 cooperativity and expression of ERR target genes are downregulated in human heart failure samples suggesting that dysregulation of this circuitry may contribute to congenital and acquired forms of heart failure." (PMID 35418170, 2022). "Therefore, the inhibition of GATA4 homomultimerization could serve as a potential therapeutic strategy for the development of novel drugs against heart failure." (PMID 35173540, 2022). "However, by deleting Gata4, cardiac function declines and heart failure occurs rapidly, indicating that a proper dosage of Gata4 may be the key to modulating hypertrophy in the postnatal period." (PMID 33807107, 2021). "In addition, to investigate whether the multimerization of GATA4 increases or decreases in heart failure, we intend to perform immunoprecipitation and Western blotting assays using the cardiac tissues of mice that have undergone heart failure-inducing surgery." (PMID 35173540, 2022). "Indeed, we have previously shown that hearts from Gata4 cardiac-specific targeted mice had a defect in cardiac angiogenesis following stress stimulation that then directly predisposed to heart failure, although the role of Gata6 in this process was not analyzed." (PMID 24391969, 2013). "Notably, GATA4 and MEF2C show significant increases, whereas Nkx2.5 shows a decrease compared to normal groups during heart failure progression." (PMID 42021955, 2026). "Using mouse models and cardiac tissue from human heart failure patients, we demonstrated that SORBS2 expression is consistently increased during pathological remodelling, correlates to disease severity, and is regulated by GATA4." (PMID 39957251, 2025).
heart failure (continued). "On the other hand, STAT3 activates the transcription regulator GATA4, thereby upregulating the expression of NPPA, MYH7, and MYH6, which interacted with each other to regulate the structure and function of the sarcomere, resulting in heart failure and arrhythmias." (PMID 36034815, 2022). "Interestingly, GATA4 was shown to be upregulated in human failing hearts, and its expression decreases in response to the treatment of left ventricular assist device (LVAD) in heart failure, indicating other regulatory factors exist for CIP expression control." (PMID 35369338, 2022). "In contrast, we found that overexpressed Myc bound both the promoter region and body of many cardiac-specific genes including transcription factors (Gata4, Gata6, Tbx20, Nkx2-5), structural genes (Actc1, Pln), or heart failure related genes (Nppa, Nppb), but did not induce Pol II recruitment." (PMID 27346836, 2016). "However, non-redundant functions were identified in allowing the heart to compensate and resist heart failure after pressure overload stimulation, as neither Gata4 nor Gata6 deletion was fully rescued by expression of the reciprocal transgene." (PMID 24391969, 2013). "Also, the combined domains between Bmi‐1‐RING1B and GATA4 in aging cardiomyocytes could be therapeutic targets for identifying stapled peptides in clinical applications to promote the combination of Bmi‐1‐RING1B with GATA4 and the ubiquitination of GATA4 to prevent SA‐PCH and heart failure." (PMID 35390228, 2022). "While single deletion of Gata4 or Gata6 in activated cardiac fibroblasts did not exert any phenotypic effect on cardiac function, we found a more decreased systolic function and signs of aggravated heart failure in mice with combined deletion of Gata4 and Gata6 in heart fibroblasts." (PMID 33876316, 2021). "Thus, it forms a critical feedback loop signaling pathway of β1-AR/cAMP/PKA/GATA-4/let-7/β1-AR, and the decreasing of β1-AR in CIHF is induced by β1-AR activation in early phase of CIHF, which is a kind of self-regulation of β1-AR in the course of ischemia induced heart failure." (PMID 28060734, 2017). "We have previously reported that 4/4 allele targeted mice crossed with mice containing the βMHC-cre transgene resulted in spontaneous heart failure at baseline and complete lethality by 16 weeks of age, hence we were not able to perform TAC stimulation on fully homozygous Gata4/6 loxP-targeted mice." (PMID 24391969, 2013).
atrial septal defect (41 papers, 2007 to 2026). Interauricular communication is a congenital malformation characterized by a communication between the atrial chambers of the heart. "Further supporting this notion, Bu and colleagues described a pathogenic M310T variant also located in the NLS domain of GATA4, which segregated with congenital atrial septal defects (ASDs) and arrhythmias in a three-generation pedigree." (PMID 40430071, 2025). "The second one is a substitution also in the -6 nucleotide in the GATA4 gene that is causing atrial septal defects with an autosomal dominant heredity." (PMID 37344844, 2023). "Pathogenic variants in the cardiac transcription factor GATA Binding Protein 4 (GATA4) are known to cause developmental heart defects including atrial septal defect, ventricular septal defect, atrioventricular septal defect, and tetralogy of Fallot." (PMID 38049901, 2023). "The earliest application of sequencing technologies to the clinic has been focused on syndromic CHD or CHD with known monogenic inheritance, such as GATA4 mutations, which are now known to be associated with septal defects." (PMID 38205435, 2023). "A GATA4 mutation has been found in a child with atrial septal defect and neonatal diabetes caused by pancreatic agenesis." (PMID 33865372, 2021). "Such a GATA4 mutation reduced GATA4 protein level, resulting in atrial septal defect, and led to β-thalassemia when present in the β-globin gene." (PMID 33102613, 2020). "Human genetic studies have implicated haploinsufficiency of GATA4 in human CHDs, such as atrial septal defects (ASD), ventral septal defects (VSD), and tetralogy of Fallot (TOF)." (PMID 31120883, 2019). "Nineteen mutations in GATA4 have been studied in patients with atrial septal defect (ASD), ventricular septal defect (VSD), and Fallot's tetralogy (Mattapally, Nizamuddin, Murthy, Thangaraj, and Banerjee (2015))." (PMID 30834692, 2019). "Mutations in GATA4 that are associated with pulmonic stenosis in the setting of an atrial septal defect have been reported in four separate families, three families with p.Gly296Ser mutations and one family with a p.Lys319Glu mutation." (PMID 31138536, 2019). "The GATA4 p.Gly296Ser mutation was identified in a large family with inherited atrial septal defect and partially penetrant pulmonic valve stenosis." (PMID 31138536, 2019). "We identified a heterozygous p.(R284H) variant of GATA4 in a Japanese family with atrial septal defect, including boys with apparently normal male sex development." (PMID 30455927, 2018). "The GATA4 gene is an important factor in the cardiac gene network and mutations in GATA4 have been confirmed to be associated with the occurrence of atrial septal defect (ASD)." (PMID 25873328, 2015). "A heterozygous mutation (mG295S) in the Gata4 gene disrupts these protein interactions, resulting in cardiac defects like atrial septal defects (ASD), AV septal defects (AVSD) and myocardial thinning beginning at E11.5." (PMID 23457456, 2013). "Since the year it was identified as a genetic cause of septal defects, GATA4 has been extensively screened for CHD-specific variations." (PMID 23626780, 2013). "Subsequently, two other families have been reported with a GATA4 G296S mutation, and affected members display a similar phenotype of atrial septal defects and incompletely penetrant pulmonary valve stenosis." (PMID 22589735, 2012). "The GATA4 G296S mutation has been associated with atrial septal defects and pulmonary valve stenosis in multiple human families." (PMID 22589735, 2012). "We previously published a highly penetrant autosomal dominant mutation (G296S) in GATA4, which was associated with atrial and ventricular septal defects in a large kindred." (PMID 22589735, 2012).
atrial septal defect (continued). "One notable study demonstrated that GATA4 mutations associated with atrial septal defects (ASDs) disrupt transcriptional networks responsible for atrial specification, impairing key signaling pathways such as Sonic Hedgehog and altering TBX5 recruitment at cardiac enhancers." (PMID 40564627, 2025). "Accordingly, GATA4 is important in the differentiation of cardiomyocytes; and known pathogenic variants in GATA4 contribute to developmental heart defects including atrial septal defect, ventricular septal defect, atrioventricular septal defect, and tetralogy of Fallot." (PMID 38049901, 2023). "Variants in GATA4 have been implicated in cardiac septal defects." (PMID 38205435, 2023). "Several such mutations have been identified with developmental disorders such as atrial septal defect (ASD) associated with a mutation in GATA4 gene, and genes TBX5, TBX20 have been identified to result in ventricular septal defect (VSD) and left ventricular non-compaction (LVNC)." (PMID 35317745, 2022). "The authors also reported the E359del variation of GATA4 in 5 members of another family with the autosomal dominant transmission of atrial septal defect in 4 generations, indicating GATA4 as a genetic cause of atrial septal defect." (PMID 35047139, 2021). "We previously reported a highly penetrant GATA4 p.Gly296Ser mutation in familial, congenital atrial septal defects and pulmonic valve stenosis and showed that mice harboring the orthologous G295S disease-causing mutation display not only atrial septal defects, but also semilunar valve stenosis." (PMID 31138536, 2019). "Another interesting aspect from these human genetics reports is the finding of GATA4 mutations in patients with both pulmonic valve stenosis and an atrial septal defect, supporting the idea that GATA4 mutations only cause pulmonic valve stenosis in the setting of an atrial septal defect." (PMID 31138536, 2019). "Further querying of large databases containing CHD cohorts will be required to determine whether GATA4 variants are only associated with pulmonic valve stenosis and atrial septal defect phenotypes." (PMID 31138536, 2019). "Also authors found that nonsyndromic cardiac septal defects have been linked to mutations in GATA4 (OMIM: 600,576) (McDermott, Basson, & Hatcher, 2006)." (PMID 30834692, 2019). "Similarly, mutations in the cardiac transcription factor, GATA4, have also been linked to atrial and ventricular septal defects." (PMID 22589735, 2012). "It has also been shown that in transgenic mice transgenic mice with cardiac-selective overexpression of NEXN developed an atrial septal defect (ASD) phenotype and that NEXN mutations in ASD patients inhibit GATA4." (PMID 39000221, 2024). "Mutations in key transcription factors such as GATA4, NKX2-5, and TBX5, which regulate cardiac development, have been linked to defects such as atrial and ventricular septal defects and TOF." (PMID 40564627, 2025). "Genetic mutations in cardiac transcription factor genes such as NKX2-5, GATA4, TBX5 and MYH6, located in chromosome 14q12, have been associated with atrial septal defects." (PMID 40843896, 2025). "Other potentially involved genes (GATA Binding Protein 4, GATA4; T-Box Transcription Factor 20, TBX20; NK2 Homeobox 5, NKX2-5; Zic Family Member 3, ZIC3) were initially recognized as pathogenic for Atrial Septal Defects (ASD)." (PMID 34946902, 2021). "GATA4 gene regulatory region was investigated in the patients with atrial septal defects (ASD) (n = 332) and ethnic-matched controls (n = 336)." (PMID 34193080, 2021). "The mutations in various genes have been associated with atrial septal defects, for instance, mutations in NKX2–5, GATA4, TBX5, and MYH6." (PMID 29969989, 2018).
atrial septal defect (continued). "The majority of cases are sporadic, but some are inherited and associated with mutations in specific genes such as NKX2-5 (also associated with atrioventricular conduction defects), GATA4, TBX5 (associated with Holt–Oram syndrome) and MYH6 (implied in septal defects)." (PMID 40843896, 2025). "In contrast to our results and others’, the c.-6G>C variant in GATA4, which is associated with atrial septal defects, was also shown to reduce protein levels, but not mRNA levels." (PMID 39596509, 2024). "Abnormalities in GATA4 during embryogenesis or in adult life cause structural and functional anomalies in the heart, such as ventricular septal defect (VSD), atrial septal defect (ASD), patent ductus arteriosus, endocardial cushion defect, tetralogy of Fallot, and pulmonary stenosis." (PMID 39286212, 2024). "Although most cases of atrial septal defect (ASD) are sporadic, familial cases have been reported, which may be caused by mutation of transcription factor GATA binding protein 4 (GATA4)." (PMID 33413087, 2021). "Several familial studies reported that mutations in GATA4 may cause different kind of CHD i.e., atrial septal defect (ASD), ventricular septal defect (VSD), tetralogy of fallot (TOF) and pulmonary stenosis (PS)." (PMID 25928801, 2015). "The relationship between the phenotypes of CHD and the genotypes of the GATA4 mutations is very complex, although it is interesting to note that GATA4 mutations are frequently associated with septal defects,such as ASD, VSD and AVSD." (PMID 23626780, 2013). "NKX2-5, NOTCH1 and GATA4 have high confidence for nonsyndromic CHD, atrial septal defect (NKX2-5 and GATA4), aortic valve stenosis and tetralogy of fallot (NOTCH1)." (PMID 39567769, 2024). "For example, in the case of atrial septal defect (ASD) and ventricular septal defect (VSD), candidate genes can be counted: NKX2-5, GATA4, TBX20, MYH6, and TBX5, while the pathogenesis of atrioventricular septal defect (AVSD) involves genes, such as PTPN11, KRAS, SOS1, RAF1, and CRELD1." (PMID 34946970, 2021).
Tetralogy of Fallot (30 papers, 2007 to 2025). A congenital cardiac malformation comprising pulmonary stenosis, overriding aorta, ventricular septum defect, and right ventricular hypertrophy. "Concerning the cardiac defects, which are common among patients carrying a 8p duplication, a haploinsufficiency gene the GATA4, has been associated with atrial, ventricular and atrioventricular septal defect and tetralogy of Fallot." (PMID 38622524, 2024). "Abnormal expression of Gata4 can cause various fetal heart malformations, such as septal defect, tetralogy of Fallot, myocardial trabecular dysplasia, and valve malformation." (PMID 32795258, 2020). "A mutation of a residue in the vicinity of V217, E215D, has been implicated in cardiac roles of GATA4 as it has been detected in some patients with Tetralogy of Fallot." (PMID 25241353, 2014). "The GATA4 P163S variant has been previously reported and linked to tetralogy of Fallot." (PMID 39285472, 2024). "While GATA4 knockdown is embryolethal, mutations of GATA4 are associated with cardiac septal defects as well as pulmonary stenosis, but also with tetralogy of Fallot (TOF) and double outlet right ventricle (DORV)." (PMID 28228731, 2017). "Dominant GATA4 mutations cause severe CHD including atrial and atrioventricular septal defects (ASDs and AVSDs) as well as Tetralogy of Fallot." (PMID 29326753, 2017). "Previous study investigated the incidence and prevalence of GATA4, NKX2‐5, gene mutations in a large group of individuals with controtruncal defect (CTD), including 178 patients with tetralogy of Fallot, 13 patients with double–outlet right ventricle (DORV), and 11 patients with truncus arteriosus." (PMID 30834692, 2019). "Mutations in NKX2-5 (5q35.1), GATA4 (8q23.1), ZFPM2 (8q23.1), GATA6 (18q11.2), GDF1 (19p13.11), JAG1 (20p12.2), and TBX1 (22q11.21) have been reported in sporadic cases with tetralogy of Fallot; however, interaction of these genes and FMR1 gene has never been reported." (PMID 28751920, 2017). "In addition, the tetralogy of Fallot is enriched in non-Roma, with two pathogenic variants in GATA4 gene (rs56208331 and rs115099192) with increased frequencies in South Asian groups." (PMID 34220960, 2021). "NKX2-5, GATA4 and HAND1 are essential for heart development, however, little is known regarding their epigenetic regulation in the pathogenesis of tetralogy of fallot (TOF)." (PMID 24182332, 2013). "A mutation (p.Glu216Asp) in the N-terminal zinc finger was detected in 2/26 patients with Tetralogy of Fallot (TOF), and this mutation resulted in reduced transcriptional activity without affecting GATA4's ability to bind DNA, nor its interaction with ZFPM2 (FOG2)." (PMID 17592645, 2007).